NLRP3 (NLR family pyrin domain containing 3)
Diseases named in the same sentence as NLRP3 in open-access papers (continued):
Sharing a sentence is not in itself a finding about the gene and the disease.
infection (continued). "In contrast, repression of the transcription of GSDMD and NLRP3 indeed decreased host cell survival (GSDMD P value = 0.0038; NLRP3 P value = 0.0185), and GSDMD gene knockdown increased intracellular pathogen growth in S. flexneri ΔvirG infection." (PMID 34933448, 2021). "We inferred that infection with either P. bovis or P. ciferrii contributed to the assembly of ASC, Pro Caspase1, and NLRP3 during inflammasome formation." (PMID 34895324, 2021). "NLRP3 and AIM2 are known to play critical roles in inflammasome activation upon a variety of cellular infection or stress." (PMID 34006824, 2021). "Common PRRs of NOD1, NOD2, NLRP3, NLRC4, NLRC5, and AIM2 were detected using qPCR assays after 90 min of infection with A. sobria at a MOI of 10 and 2 h gentamycin treatment followed by 12 h incubation." (PMID 34513725, 2021). "Together, these data suggest that both NLRP3 and NLRC4 contribute to the inflammasome response to infection with S. Typhimurium of human macrophages." (PMID 33380493, 2021). "Our data confirm that both NLRP3 and NAIP/NLRC4 contribute to the inflammasome response in human macrophages upon infection with S. Typhimurium, but the relative contribution of various ligands of this bacterium is unclear." (PMID 33380493, 2021). "In this review, we focus on activation and regulation of the NLRP3 and AIM2 inflammasomes after exposure to MTB, as well as the effect of inflammasome activation on host defense against the infection." (PMID 33503864, 2021). "Treatment of mice with the specific NLRP3 inhibitor, MCC90, within 24 h of infection with the lethal influenza A virus (IAV), significantly increased mortality." (PMID 33652815, 2021). "Using immunofluorescence staining of ASC and NLRP3, we found that CFT073 at MOI 1 after 4 h on infection induced ASC-speck formation and that these specks were co-localized with NLRP3 in renal fibroblasts." (PMID 34944029, 2021). "Pulmonary epithelial cells exhibit increased regulation of NLRP3 (by only F11 and H37Rv strains) PYCARD (ASC) and CASP1 during early infection by clinical strains of M. tuberculosis." (PMID 34502407, 2021). "In contrast, treatment with mito-TEMPO decreased the green fluorescence intensity of NLRP3 and ASC compared to infection with either P. bovis or P. ciferrii." (PMID 34895324, 2021). "T. gondii infection time-dependently induced NLRP3 and ASC protein expression, adequately induced NLRP6 and cleaved caspase-1 expression, and moderately induced NLRC4 expression at 4 h post-infection." (PMID 33712075, 2021). "The lung homogenates from Nlrp3−/− mice showed significantly higher levels of IL-1β, IL-6, IL-10, IL-12p70, G-CSF, GM-CSF, TNF-α, and RANTES than the wild-type mice on day 3 post-infection." (PMID 34690967, 2021). "Other viruses have evolved mechanisms to utilize NLRP3 inflammasome activation to their advantage, including HIV, infection of which is enhanced by inflammasome activation due to increased production of permissive cells." (PMID 33198300, 2020). "NLRP3 inflammasome is assembled by NLRP3, ASC, and Caspase-1 after exogenous infection and endogenous signal stimulation; subsequently, there is Caspase-1 activation and the release of downstream inflammatory factors, such as IL-1β and IL-18." (PMID 32195267, 2020). "NLRP3 is a classic sensor and has been reported to drive GSDMD cleavage in response to pathogen infection; therefore, we investigated the roles of the newly discovered NLRs NLRP12 and NLRC4." (PMID 32295623, 2020). "As IL-1β production in response to both Mtb infection and LZD treatment depends largely on the NLRP3 inflammasome, we also investigated a regimen in which LZD and a small molecule NLRP3 inhibitor (MCC950) was administered between days 56 and 77 post-infection." (PMID 32477361, 2020).
infection (continued). "Further, they support the hypothesis that replication competent HSV-1 is capable of decreasing both AIM2 and NLRP3 dependent inflammasome activation because UV irradiating the virus led to significant increases in IL-18 release in both the ΔAIM2 and ΔNLRP3 lines at 24 hours post-infection." (PMID 32101570, 2020). "After infection, THP1 macrophages were fixed and stained using immuno-fluorescence labelling against NLRP3 and caspase-1 for visualization by widefield fluorescence microscopy." (PMID 32230726, 2020). "Our data suggested that Nlrp3 inflammasome activation and pyroptosis participated in the proinflammatory response upon SS2 infection." (PMID 32922370, 2020). "As expected, the levels of NLRP3 and NLRC4 were significantly increased after infection with S. Typhimurium." (PMID 33384666, 2020). "As our approach monitors all infection steps from the gut lumen to the mLN, these data should exclude an impact of IEC and phagocyte NLRP3 and Caspase-11, alike." (PMID 31953493, 2020). "Interestingly, infection is not a prominent feature of the spectrum of conditions caused by gain-of-function variants in NLRP3, suggesting that overactivity of NLRP3 is likely not sufficient to predispose an individual to RVVC." (PMID 32185141, 2020). "Upon infection of mouse or human macrophages, L. monocytogenes can be detected by multiple inflammasomes, including AIM2, NLRC4, NLRP3, NLRP6, caspase‐11 and NLRP1B." (PMID 32185892, 2020). "The NLRP3 inflammasome plays a critical role in guarding against IAV infection and reducing lung damage consequent to infection." (PMID 33072117, 2020). "We investigated the impact of infection and parasite opsonization on the TLR/NLRP3-activated, canonical NF-κB pathway, and on the CD40/TNFRSF1b-activated, alternative NF-κB pathway linked to cross-presentation." (PMID 32582184, 2020). "Collectively, these results indicate that the production of IL-18, while mediated by NLRP6 in the initial phase of infection, is then dependent on NLRC4, more than NLRP3." (PMID 31681274, 2019). "By using western blot we found that NLRP3 was required for CASP1 (p20) and IL-1β (p17) cleavage in response to infection." (PMID 31479495, 2019). "The NLRP3-ASC-caspase-1 inflammasome rapidly processed cytokines and GSDMD following infection by virulent EPEC." (PMID 31018119, 2019). "SCs responded to infection with increased expression of mRNAs for IFNβ, IFNλ, IFIT-1, Mx1, NLRP3, IL-23A, IL-6 and TNFα." (PMID 31289325, 2019). "In contrast, infection with less-virulent HSV-1 strains (KOS, RE or F) or with the clinical isolate KOS63 induced a lower expression level of NLRP3 and IFI16 inflammasomes." (PMID 31367214, 2019). "Thus, the development of targeted NLRP3 inflammasome site-specific therapeutics may be more beneficial in suppressing inflammasome-associated disease whilst not predisposing to infection." (PMID 31590215, 2019). "Together, these results indicated that upon infection of HSCs, B. abortus triggers AIM2 and NLRP3 inflammasome activation with concomitant IL-1β secretion in a mechanism that is dependent on a functional T4SS and DNA." (PMID 32038610, 2019). "The NLRP3 (NOD-like receptor family, pyrin domain containing 3) inflammasome is a protein complex that orchestrates immune responses to infection and cell stress through activation of caspase-1 and inflammatory cytokines." (PMID 29747649, 2018). "We found that mPDCA-1-mediated depletion of pDCs in Aim2−/−, Nlrp3−/−, Casp1−/−, and Il1r1−/− mice markedly decreased serum levels of IFN-α/β at day 1 after YM infection, compared with those treated with control antibody." (PMID 30470758, 2018). "Nlrp3−/− mice were given SR140333 or vehicle intra-peritoneally, one hour before infection or 30 minutes after infection with CY-17." (PMID 30030504, 2018). "In the work described here, we examined the role of NLRP3, ASC, and caspase-1/11 in mediating host immune defense against N. caninum in the acute periods of infection." (PMID 30105037, 2018).
infection (continued). "NOD-like receptor family pyrin domain containing 3 (NLRP3) is another cryptococcal recognizing PRR and has been shown in mice to be involved with leukocyte infiltration in the lung during infection." (PMID 29670625, 2018). "Inflammasome, a multiprotein complex, consisting of NLRP3, ASC and procaspase is generated in response to infection, cellular damage and metabolic dysregulation." (PMID 30510203, 2018). "Inhibition of the NLRP3 inflammasome by CVL may reduce the pathogenic effects induced by the metabolic danger signals, and the side effects of NLRP3 inflammasome inhibition (e.g., increased susceptibility to infection) can be compensated for by other inflammasomes." (PMID 30186288, 2018). "In an infection model for influenza virus, type I IFN initiates an anti-influenza virus effect through an RIG-I/TLR3/NLRP3 dependent pathway." (PMID 30013955, 2018). "In contrast, Nlrp3−/−, Casp1/11−/−, and Asc−/− mice had diminished numbers of activated CD8+ CD9+ T cells at 2 and 4 weeks that were totally abolished at 10 weeks of infection." (PMID 28740491, 2017). "From 2 to 10 weeks of infection, increased frequencies of IFN-γ+ and IL-17+ CD4+ T cells were seen in the lungs of WT mice when compared with Nlrp3−/−, Casp1/11−/−, and Asc−/− mice." (PMID 28740491, 2017). "Using our juvenile mouse model of IAV infection, we show that inhibition of the NLRP3 inflammasome with the small molecule inhibitor, MCC950, beginning 3 days after infection with IAV, improves survival in juvenile mice." (PMID 28740490, 2017). "We have further studied the expression of intracellular pro-IL-1β, IFN-γ, IL-4, IL-17, and TGF-β cytokines by CD4+ and CD8+ T cells in the lungs of infected WT, Nlrp3−/−, Casp1/11−/−, and ASC−/− mice at 48 h, 2, 4, and 10 weeks of infection." (PMID 28740491, 2017). "The MMP-7 response to infection and the decrease in ASC and NLRP-3 levels were confirmed by Western blot analysis." (PMID 27732661, 2016). "Another primary function of NLRP3 may be in infection, but this has evolved to be largely redundant with other inflammasomes or inflammasome-independent mechanisms of IL-1 production, likely due to the selection pressure exerted by pathogens attempting to subvert NLRP3." (PMID 27551512, 2016). "Previous studies addressing HAdV vector infection of THP-1 cells and murine macrophages reported the activation of the NLRP3 inflammasome." (PMID 27636895, 2016). "Given that ASC-Cerulean is an immortalized cell line in which NLRP3 and ASC are overexpressed, it was important to optimize the infection conditions to closely mimic the response observed in primary BMDMs." (PMID 27303738, 2016). "The present study showed that integrin β1 mediates HGPg infection-induced SREBP-1c and NLRP3 expression through the activation of JAK2 and phosphorylation of Akt and p70S6K." (PMID 28083517, 2016). "First, the inhibition of Akt and p70S6K phosphorylation in HGFs through pretreatment with inhibitors, or infection with DN-Akt, abolished HGPg-induced SREBP-1c and NLRP3 expression, as well as IL-1β secretion." (PMID 28083517, 2016). "Although the majority of macrophages were infected at the multiplicity of infection (MOI) used (3 Candida cells per macrophage), only a proportion of up to 22% of them activated the NLRP3 inflammasome." (PMID 27303738, 2016). "On assessing NLRP3 or NLRC4 gene or protein expression, it was found that NLRP3 expression was robust during the first week of either infection with a decline thereafter." (PMID 26972847, 2016). "Infection was accompanied by strong mucosal IL-1β staining in bladder tissue sections in C57BL/6 WT mice, Asc-/- and Nlrp3-/- mice after 24 hours." (PMID 27732661, 2016). "Development of novel therapies that specifically target the NLRP3 inflammasome may therefore provide an effective treatment to reduce the mortality associated with pathogenic IAV, and offset the ineffectiveness of current antiviral treatments in the later stages of infection." (PMID 27283237, 2016).
infection (continued). "We then assessed whether YopM is able to mediate the stabilization of endogenous NLRP3 under physiological conditions by analysis of NLRP3 protein kinetics in response to bacterial infection, and observed that NLRP3 protein levels increased in WT Y. pestis-infected BMDMs within 3 h post infection." (PMID 27929533, 2016). "To clarify the role of the AIM2 and NLRP3 inflammasomes in M. bovis-infected THP-1 macrophages, we quantified their expression following infection." (PMID 27043315, 2016). "At day 3 post-infection, although limited, PMN death was evident and comparable between wildtype, Asc-/-, and Casp1/11-/- mice, but reduced in Nlrp3-/- mice as assessed by 7-AAD staining." (PMID 27926940, 2016). "In contrast, the extracellular model of infection revealed that S. aureus LukAB killed monocytic cells in a CD11b-, ASC- and NLRP3-dependent manner." (PMID 26069969, 2015). "In a murine model of in utero infection, hyperpigmented GBS strains induced fetal injury in both an NLRP3 inflammasome-dependent and NLRP3 inflammasome-independent manner." (PMID 25750210, 2015). "NCF4 (OMIM 601488) which transcribes a subunit (p40-phox) of NAPDH oxidase which activates the NLRP3 inflammasome, and NLRP3 (OMIM 606416) were both induced by PBA during infection, at 24 and 72 hrs, respectively (P≤0.026)." (PMID 26133770, 2015). "Immunostaining of human macrophage-like cells following infection revealed limited formation of inflammasome foci with constituents of total caspase-1, ASC and NLRP3 in the presence of NleA." (PMID 26332984, 2015). "MHV-3 infected PEMs and RAW264.7 cells exhibited with a significantly enhanced NLRP3, ASC, pro-Caspase-1 and its activated form (Caspase-1 p20) within 12h of MHV-3 infection." (PMID 26367131, 2015). "Here, we provided the basic data of expression pattern and histological distribution of NLRP3, IL-1β and TNF-α in lung and brain during infection in BALB/c mice by H9N2 avian influenza virus strains with only a difference at site 627 in PB2." (PMID 25547136, 2014). "The results showed that the expression level of NLRP3, IL-1β and TNF-α changed in the lung and brain of BALB/c mice after infection by VK627 and rVK627E." (PMID 25547136, 2014). "In infected groups, the expression level of NLRP3, IL-1β and TNF-α increased rapidly at 3 dpi and VK627 infection were higher than that of rVK627E." (PMID 25547136, 2014). "In this study, the authors showed that following infection, mice were hyper-responsive to E. coli-derived LPS in a mechanism that is dependent on NLRP12/NLRP3 inflammasome activation." (PMID 25329161, 2014). "The expression level of NLRP3 in the control was significantly lower than rVK627E and VK627 infection group (P < 0.05) at 1 dpi." (PMID 25547136, 2014). "In the brain, expression level of NLRP3 rose after VK627 and rVK627E infection compared with the control." (PMID 25547136, 2014). "At 6 and 30 h after infection ASC and NLRP3 expression in brain homogenates appeared upregulated as compared to saline inoculated mice." (PMID 23902681, 2013). "The NLR family member proteins NLRP3 and NLRC4 are known to recognize infection with various pathogens and to mediate caspase-1 activation by forming a complex with adaptor protein ASC." (PMID 23357873, 2013). "In this study, we found that murine bone marrow-derived dendritic cells responded to P. brasiliensis yeast cells infection by releasing IL-1β in a spleen tyrosine kinase (Syk), caspase-1 and NOD-like receptor (NLR) family member NLRP3 dependent manner." (PMID 24340123, 2013). "WT and NLRP3 KO BMDMs were infected with RSV and at 12 h and 24 h post-infection time periods medium supernatant was collected to assess IL-1β levels by ELISA." (PMID 22295065, 2012). "To identify the NLR involved in IL-1β secretion, we infected bone marrow-derived wild type (wt) and knockout macrophages in NLRC4, NLRP3, ASC and Caspase-1 (all from C57BL/6 mice background) at MOI of 50 and quantified the IL-1β produced 24 h post-infection." (PMID 22848580, 2012).
infection (continued). "Therefore, the findings of this study suggest that previous effects of AbM that were observed against tumors and infection may be attributed to the ability of AbM to both enhance IL-1β transcription and stimulate NLRP3 inflammasome-dependent caspase-1 activation." (PMID 22844468, 2012). "Since mitochondrial ROS was found to be important in NLRP3 inflammasome activation by MSU, alum, and ATP, we first measured the kinetic changes in ROS-producing mitochondria after infection with EMCV." (PMID 22916014, 2012). "Taken together these results show that infection of macrophages and dendritic cells with B. pseudomallei leads to activation of the NLRC4 and NLRP3 inflammasomes." (PMID 22241982, 2011). "Previous reports have demonstrated activation of both NLRP3 and NLRC4 inflammasomes in response to infection with Legionella pneumophila, Listeria monocytogenes, and Salmonella typhimurium." (PMID 22241982, 2011). "We observed a significant reduction in intracellular bacterial load beginning at 18 h post-infection (hpi), which continued through 96 hpi; this response was partially attenuated in BMDMs lacking NLRP3." (PMID 42267988, 2026). "Analysis of differentially expressed genes in the LC group compared with the CC group at day 90–180 after infection identified an increase of multiple proinflammatory markers, such as IL6, NLRP3, TNF, JAK2, CSF2, IL1B and IL10, in the LC compared with the CC group." (PMID 41388153, 2026). "The NLRP11 protein is only expressed in primates and participates in the activation of the canonical NLRP3 and non-canonical NLRP3 inflammasome activation after infection with gram-negative bacteria." (PMID 40272180, 2025). "Results presented here further suggest that the infecting Mtb strain differentially affects the expression of HIF‐1α and NLRP3 inflammasome activation network genes and contributes to differential outcomes of infection (i.e., progressive vs. nonprogressive)." (PMID 41287823, 2025). "Direct stimulation with ATP and LPS failed to fully activate the NLRP3 inflammasome in both HBECs and the 16HBE cell line, while direct infection with PsA induced only minimal activation." (PMID 41395250, 2025). "Also, it was proved that infection with porcine reproductive and respiratory syndrome virus (PRRSV) induced pyroptosis and the secretion of IL-1β by activating the NLRP3 inflammasome." (PMID 40593504, 2025). "ROS activate NLRP3 in macrophages, triggering their assembly and the synthesis of compounds like the chemokine (C-C motif) ligand 2 (CCL2, formerly termed monocyte chemoattractant protein-1, MCP-1), which recruits immune cells to the infection site." (PMID 40723899, 2025). "A significant downregulation of HIF1A, NLRP3, GBP1 and ASC, and upregulation of IL1B was observed in HIF1A‐KD macrophages, while downregulation of ASC was noted in GBP1‐KD macrophages infected with HN878, compared with CDC1551 infection." (PMID 41287823, 2025). "Upon infection, a progressive increase in Akkermansia and a transitory expansion of Lachnospiraceae were observed in WT mice but not in NLRP3−/− mice." (PMID 41123715, 2025). "This indicates that NLRP3 activation may play a protective role in promoting cell survival and suppressing apoptosis during DMV/1639 infection." (PMID 40284946, 2025). "Additionally, as a downstream product of the NLRP3 inflammasome activation pathway, caspase-1 was evaluated, and accumulation of this protein was observed in the DENV-infected cells 24 and 36 h post-infection." (PMID 41471247, 2025). "Here, we used both in vivo chicken infection models and in vitro primary renal epithelial cell cultures and found that IBV activates the NLRP3 (NOD-like receptor family, pyrin domain containing 3) inflammasome, leading to the maturation and secretion of IL-1β (interleukin-1 beta)." (PMID 41334910, 2025).